PLCL2 (phospholipase C like 2)
Description:
May play an role in the regulation of Ins(1,4,5)P3 around the endoplasmic reticulum.
Synonyms: KIAA1092; PLCE2
Tractability: PROTAC: ubiquitination databases record sites on it; its protein half-life has been measured.
Gene: Protein-coding gene on chromosome 3 (16,802,651 to 17,090,604, forward strand). Ensembl gene ENSG00000154822.
Subcellular location: Cytoplasm
Gene Ontology:
Molecular function: GABA receptor binding; protein binding; inositol 1,4,5 trisphosphate binding; phosphatidylinositol-4,5-bisphosphate phospholipase C activity; phosphoric diester hydrolase activity
Biological process: gamma-aminobutyric acid signaling pathway; negative regulation of cold-induced thermogenesis; phosphatidylinositol metabolic process; phosphatidylinositol-mediated signaling; regulation of synaptic transmission, GABAergic; release of sequestered calcium ion into cytosol; intracellular signal transduction; lipid metabolic process; signal transduction
Cellular component: cytoplasm
Genetic constraint (gnomAD): Loss-of-function variants: 2 observed, 69.1 expected, observed/expected ratio (o/e) 0.0289, 90% interval 0.011 to 0.091. The upper end of that interval is the gene's LOEUF score, 0.091, which puts it in group 1 of 6, group 1 being the genes least tolerant of losing a copy. Missense variants: 730 observed, 1,218.7 expected, observed/expected ratio (o/e) 0.6, 90% interval 0.56 to 0.64. Synonymous variants: 391 observed, 434.21 expected, observed/expected ratio (o/e) 0.9, 90% interval 0.83 to 0.98.
Homologues: Orthologues: chimpanzee PLCL2 (100% identical), macaque PLCL2 (99% identical), dog PLCL2 (98% identical), pig PLCL2 (98% identical), rat Plcl2 (97% identical), mouse Plcl2 (97% identical), rabbit PLCL2 (88% identical), guinea pig PLCL2 (83% identical), tropical clawed frog plcl2 (82% identical), zebrafish plcl2 (71% identical), Caenorhabditis elegans pll-1 (38% identical), Caenorhabditis elegans plc-3 (23% identical), and 3 more. Paralogues in human: PLCL1 (62% identical), PLCH2 (32% identical), PLCH1 (31% identical), PLCD4 (26% identical), PLCE1 (26% identical), PLCD1 (25% identical), PLCB1 (24% identical), PLCD3 (24% identical), PLCB4 (23% identical), PLCG1 (23% identical), PLCB2 (23% identical), PLCB3 (23% identical), and 2 more.
Diseases named in the same sentence as PLCL2 in open-access papers:
PLCL2 is named in the same sentence as 23 diseases in open-access papers, as found by Europe PMC text mining. Sharing a sentence is not in itself a finding about the gene and the disease. The quoted sentences say what the papers report.
systemic sclerosis (4 papers, 2015 to 2020). A chronic disorder, possibly autoimmune, marked by excessive production of collagen which results in hardening and thickening of body tissues. "Some of these genes have been previously implicated inautoimmune disease: PADI2 expression has been demonstrated to correlatewith arthritis severity in mice (Johnsen etal., 2011), LGALS1 damages cartilage via inflammationin osteoarthritis and PLCL2 has been associated with systemic sclerosis." (PMID 29360927, 2018). "In studies of Plcl2-deficient mice, it has been shown that Plcl2 acts as a negative regulator of B cell receptor signalling and humoral immune responses, and in humans is involved in metabolism and implicated in autoimmune diseases such as psoriasis, rheumatoid arthritis, and systemic sclerosis." (PMID 30134952, 2018).
rheumatoid arthritis (3 papers, 2018 to 2023). A chronic, systemic autoimmune disorder characterized by inflammation in the synovial membranes and articular surfaces. "GWAS catalog of PLCL2 SNP rs4602367-A reported the association with rheumatoid arthritis." (PMID 36817779, 2023).
atherosclerosis (2 papers, 2020 to 2021). A disease characterized by the build-up of fatty material and calcium deposition in the arterial wall resulting in partial or complete occlusion of the arterial lumen. "Because atherosclerosis is the most common pathological change in stroke and myocardial infarction, we hypothesized that associations between PLCL2 gene polymorphisms and IS may exist in MetS patients." (PMID 35126281, 2021). "The unique features of the PLCL2 in calcium signaling pathway and subsequently in atherosclerosis led us to speculate that it may associate with myocardial infarction." (PMID 33510879, 2020). "Then, it is probable that PLCL2 gene plays its role as a promoter of the immune reactions leading to atherosclerosis." (PMID 33510879, 2020). "Fourth, the signaling pathway and the function of PLCL2 in atherosclerosis remain largely unknown." (PMID 35126281, 2021).
autoimmune disease (2 papers, 2015 to 2018). A disorder resulting from loss of function or tissue destruction of an organ or multiple organs, arising from humoral or cellular immune responses of the individual to their own tissue constituents. "We found that candidate variants at several risk loci are methylation quantitative trait loci (mQTLs), including mQTLs for DENNDIB, PLCL2, IRF5 and TNFRSF1A, all genes that are implicated in risk for other autoimmune diseases." (PMID 26394269, 2015).
myocardial infarction (2 papers, 2020 to 2021). Gross necrosis of the myocardium, as a result of interruption of the blood supply to the area, as in coronary thrombosis. "The PLCL2 gene is located on chromosome 3p24.3 and has been identified as a novel susceptibility site for myocardial infarction in Japanese populations." (PMID 35126281, 2021). "A previous GWAS reported that in the PLCL2 gene, rs4618210 was associated with myocardial infarction." (PMID 35126281, 2021).
AIDS (1 paper, 2015). A syndrome resulting from the acquired deficiency of cellular immunity caused by the human immunodeficiency virus (HIV). "Therefore, our findings imply that this locus might contribute to several AIDs; this is an observation that must be confirmed by denser mapping and additional functional experiments to further increase our understanding of the role of PLCL2 in AIDs and SSc." (PMID 25880423, 2015).
autism (1 paper, 2023). Persistent deficits in social interaction and communication and interaction as well as a markedly restricted repertoire of activity and interest as well as repetitive patterns of behavior. "Even though, PLCL2 SNP rs4602367-A was not reported on autism, a recent study revealed the association of PLCL2 SNPs (rs6800583 and rs73139272) with autism." (PMID 36817779, 2023).
fungal infection (1 paper, 2022). "However, the role of PLCL2 gene in mitochondrial dysfunction and the consequences on the ROS production capacity, and, by extend, to the increasing risk to a fungal infection, warrants further investigation." (PMID 35834984, 2022).
lymph node metastasis (1 paper, 2026). "By integrating DEGs and SMGs, PLCL2 was identified as a candidate gene potentially associated with both lymph node metastasis and prognosis." (PMID 42193406, 2026).
prostate carcinoma (1 paper, 2021). A carcinoma that arises from epithelial cells of the prostate gland. "Interestingly, a previous study identified PLCL2 as part of a 23-gene expression panel that predicts metastatic lethal prostate cancer outcomes in patients with localised disease treated surgically thus, further strengthening the possible association of this circRNA with prostate cancer." (PMID 34945002, 2021).
psoriatic arthritis (1 paper, 2015). Joint inflammation associated with psoriasis. "The PLCL2 rs4535211 variant has been reported in RA and psoriatic arthritis." (PMID 25880423, 2015).
Stroke (1 paper, 2021). Sudden impairment of blood flow to a part of the brain due to occlusion or rupture of an artery to the brain. "Subsequent investigations are needed to verify whether the PLCL2 gene can be a target for a novel therapeutic way to prevent stroke." (PMID 35126281, 2021).
tumor (4 papers, 2014 to 2025). "These genes include tumor suppressors or candidates (VHL, CTDSPL, LRRC3B, ALDH1L1, and EPHB1) and genes that were not previously considered as cancer-associated (e.g., LRRN1, GORASP1, FGD5, and PLCL2)." (PMID 24977159, 2014). "The COGS model includes genes such as AP1M2, PLCL1, PLCL2, ITGB3 and BSPRY, whose altered expression could contribute to tumorigenesis and tumor progression." (PMID 40457272, 2025). "These expression alterations in PLCL1, PLCL2 and ITGB3 could could potentially influence tumor development and tumor progression." (PMID 40457272, 2025).
cancer (2 papers, 2014 to 2015). A tumor composed of atypical neoplastic, often pleomorphic cells that invade other tissues. "But there are also a number of genes which have not been previously reported as involved in cancer development, such as LRRN1, GORASP1, FGD5, and PLCL2." (PMID 24977159, 2014).
infection (1 paper, 2022). The state of being infected such as from the introduction of a foreign agent such as serum, vaccine, antigenic substance or organism. "PLCL2 has been identified as a susceptibility gene, so inhibition of PLCL2 expression may suppress the infection of P. multocida." (PMID 35321408, 2022).
PLCL2 also shares sentences with these, for which no sentence is quoted: Arthritis (1 paper); Autoimmunity (1); metabolic syndrome (1); multiple sclerosis (1); Obesity (1); osteoarthritis (1); Primary biliary cirrhosis (1); psoriasis (1).